HSPA8 (heat shock protein family A (Hsp70) member 8)
Diseases named in the same sentence as HSPA8 in open-access papers (continued):
Sharing a sentence is not in itself a finding about the gene and the disease.
tumor (continued). "First, we found that HSPA8 and DEK had the strongest correlation with the ESTIMATE score among 36 known histone chaperones, indicating that these histone chaperones are most closely related to tumor immunity in HCC." (PMID 36768989, 2023). "In conclusion, HSPA8 and DEK greatly affect the tumor immunity of HCC and could potentially be regarded as biomarkers for precisely predicting the effect of immunotherapy in HCC." (PMID 36768989, 2023). "We then explored the correlation between the expression of the two genes and the abundance of tumor-infiltrating lymphocytes (TILs) in TISIDB and found that the expression of HSPA8 was positively correlated with the abundance of TILs in HCC, whereas the expression of DEK showed the opposite trend." (PMID 36768989, 2023). "In addition, through the analysis of the expression of HSPA8 in most tumor cells in the CCLE database, it can be confirmed that the expression of HSPA8 in BC cells is significantly higher than that in other tumor cells." (PMID 36452344, 2022). "Hsp70s, including HSPA8, HSPA2, and HSPA1B, could be either tumor-promoting or tumor-suppressing depending on cell identity and context." (PMID 36120453, 2022). "Interestingly, STMN1 and ANGPT2 were significantly positively correlated with tumor purity, whereas RAP1A, FLT3, HSPA8, and PGF were all significantly negatively correlated with tumor purity." (PMID 34178637, 2021). "HSPA8 and HSP90AA1, representative molecular chaperones, have a wide variety of effects, such as prevention of unfolded-protein aggregation, chaperone-mediated autophagy, and promotion of tumor cell proliferation." (PMID 34151031, 2021). "Moreover, heat shock proteins (HSPs) including HSPA8, HSPA9, and HSPD1 in tumor tissues displayed aberrant lysine acetylation modification." (PMID 33093847, 2020). "On the protein level, we validated these hub genes expressions of normal tissues and tumor tissues through the HPA database.HSPA8 and HSPB8 expressed higher in tumor tissues than that in normal tissues, while SERPINA1 and DIRAS3 expressed higher in normal tissues against tumor tissues." (PMID 34876005, 2021). "We also detected the other screened proteins, such as Grp75 and Hspa8/Hsc71 by coimmunoprecipitated with CD24, and found that these two proteins were also interacted with CD24, but no evidences suggested that both two proteins were involved in tumor angiogenesis." (PMID 27494878, 2016). "In addition, HSPA8 and P4HA1 were screened out as the potential modulating factors to glycolysis as their expression were highly correlated with glycolysis score and glycolysis genes, which enables future efforts for therapeutic options to block the glycolysis and control tumor progression." (PMID 32635458, 2020).
infection (58 papers, 2008 to 2025). The state of being infected such as from the introduction of a foreign agent such as serum, vaccine, antigenic substance or organism. "Our lab previously showed that the Legionella pnuemophila (L.p.) kinase LegK4 phosphorylates cytosolic human Hsp70 (Hsc70; HSPA8) at T495 during infection, increasing its association with polysomes and globally reducing protein synthesis." (PMID 40950225, 2025). "Consistently, NHS ester-labeled ASFV particles colocalized with HSPA8 and p72 during the early phase of infection." (PMID 39688418, 2025). "As the PRRSV strain used above was PRRSV-2 strain BJ-4, we next investigated the role of HSPA8 on PRRSV-1 strain GZ11-G1 infection." (PMID 35138165, 2022). "The HSPA8 protein level was substantially decreased in OGD/R-induced primary astrocytes after infection with LV-sh-HSPA8 (p < 0.05)." (PMID 34362408, 2021). "To illustrate the kinetics of the infection process and HSPA8 expression in infected neurons, we analyzed viral proteins in conjunction with HSPA8 at different time points." (PMID 34769416, 2021). "Infection of IBV was significantly reduced in anti HSPA8 polyclonal antibody pretreated cells at both 1 hpi and 24 hpi." (PMID 32765462, 2020). "In the case of infection inhibition assay, the amount of viral RNA was significantly reduced in HSPA8 antibody pretreated cells compared to the control IgG pretreated cells." (PMID 32765462, 2020). "Other proteins identified of infection include HSPA8, also known as heat shock cognate 70 (Hsc70), known for its role in vesicle uncoating in the later stage of endocytosis." (PMID 32753727, 2020). "Similar result was observed in Western blot analysis which showed that infection of IBV was significantly inhibited by HSPA8 antibody compared to the control IgG." (PMID 32765462, 2020). "Five unique heat shock proteins (HSP75, HSP90A, HSPA2, HSPA5 and HSPA8) were identified during rNA-wt infection." (PMID 28079188, 2017). "In concordance with those findings we observed a very similar phenotype in MDA-MB-231 after efficient HSPA8 knock-down at eight days post-infection." (PMID 20051122, 2010). "Our latest study showed that infection with PRRSV induced a significant increase in the expression of HSPA8 and HSP90AB1, while matrine treatment could significantly reverse it, and the number of PRRSV viruses also decreased." (PMID 37511286, 2023). "Given the evidence above, HSPA8 should be considered a strong candidate for involvement in interactions between hosts and avian poxvirus, but further work is needed to understand the mechanistic basis for how variation at this locus affects infection." (PMID 35395699, 2022). "For example, human HSPA8 (Hsc70) used to be described as a constitutive gene, but it is now widely accepted that this gene is upregulated by cellular stresses including inflammation and infection." (PMID 36120474, 2022). "However, infection with LV-sh-HSPA8 efficiently suppressed NF-κB and NLRP3 inflammasome activation (p < 0.05)." (PMID 34362408, 2021). "To check whether HS on cell membrane may have influenced IBV S protein binding to HSPA8, we performed the binding blocking assay and infection inhibition assay based on removal of HS by using heparanase." (PMID 32765462, 2020). "The results of binding blocking assay and infection inhibition assay showed that recombinant protein HSPA8 and antibody to HSPA8 could inhibit IBV M41 infection of chicken embryonic kidney (CEK) cells." (PMID 32765462, 2020). "Binding blocking assay and infection inhibition assay showed that recombinant HSPA8 protein and antibody against HSPA8 could inhibit the infection of IBV M41 and Beaudette strains in CEK and Vero cells, respectively." (PMID 32765462, 2020). "We found that at 4 h post-infection (p.i.), NP in the nucleus were observed in 60% of scrambled shRNA-treated cells, but only detected in 20% of HSPA5-specific treated cells and 10% of HSPA8-specific shRNA-treated cells." (PMID 40559543, 2025).
infection (continued). "In the current study, we uncovered the involvement of heat shock protein member 8 (HSPA8) in PRRSV attachment and internalization during infection for the first time." (PMID 35138165, 2022). "The role of HSPA8 in PRRSV infection was subsequently demonstrated and further analyses revealed that it was involved in PRRSV attachment and internalization during infection." (PMID 35138165, 2022). "Finally the results of binding blocking assay and infection inhibition assay showed that recombinant HSPA8 protein and antibody to HSPA8 could inhibit IBV Beaudette strain infection of Vero cells that were treated with heparanase to remove heparan sulfate from the cell surface." (PMID 32765462, 2020). "For example, the HSP70 isoforms HSPA1, HSPA8, and HSPA9 are required for viral entry and the translational steps of the infection." (PMID 32760390, 2020). "HSPA8 is also a host factor involved in infectious bronchitis virus (IBV, a coronavirus) infection." (PMID 34586597, 2021). "In addition, we have observed that other proteins involved in promoting or inducing apoptosis, such as DSP, PAK2, and heat shock protein family A (Hsp70) member 8 (HSPA8) proteins, were highly upregulated in rock bream RBCs upon RBIV infection." (PMID 30886611, 2019). "Hspa8 is also involved in activation of MAPK signaling during inflammation and infection." (PMID 31545822, 2019). "According to our analysis above, the difference between YN13 and YN144 in replication ability might be due to the difference between the two PEDV-infection groups in alterations of eIF4G1, hnRNPA1, HSP90B1, HSP90AB1, HSPA8, DNAJA1, and DNAJC10 in jejunums of pigs." (PMID 27916855, 2016). "However, HSPA8 overexpression in the nonpermissive cells did not facilitate IBV infection and the HSPA8 antibody did not completely abolish the infection of IBV of the host cells." (PMID 32765462, 2020).
neurodegenerative disease (30 papers, 2010 to 2025). A disorder of the central nervous system characterized by gradual and progressive loss of neural tissue and neurologic function. "HSPA8, a highly abundant member of HSP70s, was an important factor for protein refolding, which reduces the neuronal loss in the neurodegenerative disease." (PMID 25251558, 2014). "Heat shock protein 84b (part of the hsp90 class of proteins) and heat shock 70 kDa protein 8 (Hspa8) play roles in cellular homeostasis and are key players in cellular stress, including neuronal stress responses, with associations with neurodegenerative diseases." (PMID 41488750, 2025). "In addition, the converging actions of different disease forms on HSPA8 mRNA biogenesis could explain the common loss of proteostasis that characterizes diverse neurodegenerative diseases." (PMID 38168440, 2023). "Taken together, this suggests that HSPA8 is a highly attractive new target for future research on neurodegenerative diseases." (PMID 40338234, 2025). "At the center of this network was HSPA8, a regulator chaperonin-mediated autophagy inhibitor of αsyn aggregation, which has been implicated in PD, DLB, MSA, and other neurodegenerative diseases." (PMID 40122840, 2025). "Hspa8 belongs to the Hsp70 family of chaperones and exhibits a protective potential in neurodegenerative diseases." (PMID 38933267, 2024). "SY-SY5Y cells are a model for neuronal aging and neurodegenerative diseases, and we have recently shown that oxidation of HSC70/HSPA8 and UBE2D leads to premature SH-SY5Y cell senescence." (PMID 33805811, 2021). "The Hsp70 protein HSPA8 was selected because Hsp70s have been previously suspected to play critical roles in neurodegenerative disease." (PMID 26317359, 2015). "Because Hspa8 gene mutation has not been known to cause any neurodegenerative diseases either in humans or animals, our result is the first evidence that HSPA8/HSC70 is directly involved in the pathogenesis of NAD." (PMID 38384479, 2024). "The functionality of HSPA8 and GAPDH in modulating the cellular toxicity of expanded polyQ HTT has been well studied, and SNAP25 has been investigated in the context of neurodegenerative diseases." (PMID 35932982, 2022). "HSPs, including HSP90AA1, HSPA8 and DNAJB1 (all upregulated in the presence of P2RY6 antagonist) are key players in chaperone-mediated autophagy (CMA), a form of autophagy that is impaired in aging and neurodegenerative diseases." (PMID 36203578, 2022). "We selected HSPA8, CLINT1 and SGTA as candidate proteins that could potentially be recruited into pathological aggregates in neurodegenerative disease." (PMID 26317359, 2015).
neurological disease (5 papers, 2019 to 2023). "In module-5, VCP shown interaction with 5 proteins (AKTI, CAV1, HSPA8, DNM1L, TKT) functionally associated with enzyme binding processes and most of these genes are mostly related to neoplasms disorder followed by nervous system diseases." (PMID 34918006, 2022).
immune disorders (3 papers, 2019 to 2022). "And the HSPA8 expression has been found to change in many immune diseases." (PMID 36452344, 2022). "HSPA8 expression has been seen to be altered in a number of immune disorders." (PMID 31394830, 2019). "We also exemplify the interest of targeting HSPA8 to regulate pathological immune dysfunctions." (PMID 31394830, 2019). "Below we will focus our attention on immune disorders in which HSPA8 defaults have been described." (PMID 31394830, 2019). "After briefly over viewing the HSPA8 structure and functions, this short article describes the role of HSPA8 in immune disorders, and presents the current ‘toolbox’ of pharmacological agents that might be effective therapeutics in this set of indications." (PMID 31394830, 2019). "HSPA8 detects substrates that are processed by chaperone-mediated autophagy (CMA), and its expression is altered in a number of immune disorders." (PMID 34663331, 2021).
bacterial infection (2 papers, 2022 to 2023). "In C. elegans, epigenetic mark H3K4me3 is required for the response to bacterial infection, xenotoxicity and heat shock, and trimethylation of Hspa8 lys561 improves its stability and function in chaperone-mediated autophagy." (PMID 36986396, 2023).
hematologic malignancies (1 paper, 2025). "Notably, several drug-gene pairs—including those targeting CASP8, CASP10, KCNQ1, and HSPA8—are not currently approved nor under clinical evaluation for LN, representing investigational candidates with potential for future development in hematologic malignancies." (PMID 40883272, 2025).
inflammation (1 paper, 2021). Aberrant reaction of the microcirculation characterized by movement of fluid and leukocytes from the blood into extravascular tissues. "Prior studies have placed substantial emphasis on the role of heat shock protein family A member 8 (HSPA8) on postischemic myocardial inflammation and cardiac dysfunction." (PMID 34362408, 2021). "Besides, HSPA8 exacerbated the postischemic myocardial inflammation and cardiac dysfunction by NF-κB activation." (PMID 34362408, 2021).
HSPA8 also shares sentences with these, for which no sentence is quoted: colon carcinoma (10 papers); Parkinson’s (7); Rotavirus infection (6); amyotrophic lateral sclerosis (5); leukemia (5); multiple myeloma (4); renal cell carcinoma (4); Tauopathies (4); cardiovascular disease (3); osteosarcoma (3); abortion (2); acute kidney injury (2); adenoma (2); amyloid (2); Anxiety (2); Brain tumor (2); calculus (2); cardiomyopathy (2); clear cell renal cell carcinoma (2); diabetic kidney disease (2); gastric tumors (2); medulloblastoma (2); mental disorder (2); multiple system atrophy (2); neuroaxonal dystrophy (2); renal carcinoma (2); squamous cell carcinoma (2); thyroid cancer (2); urologic diseases (2); acute coronary syndrome (1).
A further 97 diseases each share a sentence with HSPA8 in 1 paper.